ZEB1 (zinc finger E-box binding homeobox 1)
Diseases named in the same sentence as ZEB1 in open-access papers (continued):
Sharing a sentence is not in itself a finding about the gene and the disease.
breast tumor (continued). "Furthermore, our previous observation that upregulation of TCF8 (ZEB1) occurs in metastatic and more undifferentiated breast tumours of the Vańt Veer's series suggest a potential link between E47/ID1 or ID4 and TCF8 expression in undifferentiated basal-like tumours." (PMID 23555842, 2013).
endometrial cancer (41 papers, 2010 to 2024). Primary or metastatic malignant neoplasm involving the endometrium (mucous membrane that lines the endometrial cavity). "ZEB1 expression was significantly associated with subtype, grade, myometrial invasion, and lymph node metastases in endometrial cancer." (PMID 34948036, 2021). "In endometrial cancer, ZEB1 may cause the down-regulation of E-cadherin expression and eventually lead to enhanced tumor cell invasion and migration ability." (PMID 33391437, 2021). "Moreover, the transcription factor ZEB1, a validated target of the mir-200 family, is up-regulated during the secretory phase in the human endometrial stroma, and its misregulation has been implicated in endometrial cancer progression." (PMID 22911744, 2012). "The Western blot results revealed that ZEB1 protein expression levels were significantly higher in the endometrial cancer cell lines than in normal endometrial epithelial cells (**P < 0.05)." (PMID 38916621, 2024). "ZEB1 mRNA expression was higher in the endometrial cancer cell lines than in the normal endometrial epithelial cell line (**P < 0.05)." (PMID 38916621, 2024). "miR-200a-3p can directly target part of ZEB1, which has the potential to be used in the therapy of endometrial cancer." (PMID 38916621, 2024). "The results indicated that the expression level of ZEB1 in the HEC-1B endometrial cancer cell line was significantly elevated after the knockdown and overexpression of miR-200a-3p (**P < 0.05)." (PMID 38916621, 2024). "qRT-PCR was also used to analyze changes in ZEB1 in the HEC-1B endometrial cancer cell line at the mRNA expression level after knocking down and overexpressing miR-200a-3p." (PMID 38916621, 2024). "ZEB1 was highly expressed in the endometrial cancer cell lines, consistent with the results of previous studies." (PMID 38916621, 2024). "Whereas in AN3CA, a cell line derived from lymph node metastatic lesion of endometrial cancer, western blot showed an increase in the epithelial marker E‐cadherin, a decrease in vimentin and Zeb1." (PMID 37387559, 2023). "It has been recently reported that ZEB1 (Zinc finger E-box binding homeobox 1) can bind to the HDGF (hepatoma-derived growth factor) promoter to stimulate HDGF transcription in EC (endometrial carcinoma) cells." (PMID 35000617, 2022). "In conclusion, our results showed that both TET3 and OGT are involved in the regulation of FOXC1, TWIST1, and ZEB1 in endometrial cancer and affect cancer cell migration and invasion." (PMID 34948036, 2021). "The impact of changes in OGT and TET3 amounts on the expression of genes involved in epithelial-mesenchymal transition (FOXA1, FOXC1, TWIST, ZEB1) in endometrial cancer cells has been analyzed." (PMID 34948036, 2021). "Expression of transcription factor ZEB1 in the stromal cells has been proven to be associated with EMT and tumor progression in urothelial and endometrial cancer." (PMID 29416615, 2018). "Ets variant 5 (ETV5) belongs to the polyoma enhancer activator 3 (PEA3) family of transcription factors and has been found to induce EMT in endometrial cancer cells by increasing the transcription of Zeb1." (PMID 26356073, 2015). "In endometrial cancer cells, miRNAs can activate or attenuate EMT and CSC by targeting PTEN and other EMT-associated genes, such as Twist1, ZEB1 and BMI-1." (PMID 25141911, 2014).
endometrial cancer (continued). "The purpose of this study was to analyze the expression of ZEB1 in endometrial biopsy and its correlation with preoperative characteristics, including lymph node metastases in patient with endometrial cancer." (PMID 25544793, 2014). "Expression of ZEB1 correlated with an aggressive phenotype in various histological types of endometrial carcinoma and was detected in the sarcomatous compartment of endometrial carcinosarcoma." (PMID 23844063, 2013). "Therefore, miR-200a-3p was negatively correlated with ZEB1 expression in endometrial cancer patients." (PMID 38916621, 2024). "Therefore, the EMT-promoting mechanism of miR-200a-3p and ZEB1 can be used to inhibit the metastatic potential of endometrial cancer, with corresponding effects in immunotherapy and chemotherapy resistance." (PMID 38916621, 2024). "It is also showed that metformin may exert inhibitory effect of EMT in endometrial cancer cells through downregulating ZEB1 expression." (PMID 29467947, 2018). "In endometrial cancer, Zeb1 decreased the expression of E-cadherin." (PMID 26356073, 2015). "ZEB1 expression in endometrial biopsy could help physicians to better predict the lymph node metastasis in patients with endometrial cancer prior to hysterectomy." (PMID 25544793, 2014). "In highly migratory and aggressive cell line of endometrial cancer, reduction of ZEB1 expression could result in reduced migratory capacity of cell." (PMID 25544793, 2014). "We also evaluated whether ZEB1 expression in endometrial biopsy could predict lymph node metastases in patients with endometrial cancer." (PMID 25544793, 2014). "In contrast, all of the TNBC and type 2 endometrial cancer lines express either one or both of these proteins in addition to ZEB1, supporting the hypothesis that they may play a role in migration in the absence of miR-200c." (PMID 21501518, 2011). "In contrast, aggressive types of endometrial cancers also showed zeb1 expression in tumor cells." (PMID 21324165, 2011). "Therefore, miR-200a-3p could regulate MET and indirectly act on the corresponding ZEB1 targets to promote the invasion and metastasis of endometrial cancer." (PMID 38916621, 2024). "However, stromal expression of ZEB1 increased in low‐grade endometrial carcinomas, epithelial expression of ZEB1 was found in high‐grade endometrial carcinomas, suggesting that aberrant expression of ZEB1 induces EMT, contributing to aggressive behaviours of malignant cancers." (PMID 27027258, 2016). "We hypothesized that ZEB1 expression increases independently of androgen in these metastatic lines and contributes to androgen-independent PCa cell proliferation, comparable to what occurs with ZEB1 expression in advanced ovarian and endometrial cancers." (PMID 22190929, 2011). "ZEB1 is an efficient transcription factor in the EMT process and is essential for activating the invasion and metastasis phenotypes of endometrial cancer." (PMID 38916621, 2024). "This study preliminarily explored the role of miR-200a-3p in endometrial cancer and demonstrated its regulatory role in the EMT process, including ZEB1 expression, which can provide a promising target for treating metastatic endometrial cancer." (PMID 38916621, 2024). "Here, we demonstrated that in endometrial cancer cells both TET3 and OGT affected the expression of genes involved in epithelial to mesenchymal transition (EMT), i.e., FOXC1, TWIST1, and ZEB1." (PMID 34948036, 2021).
endometrial cancer (continued). "Our study demonstrated that ZEB1 and Snail participate in the ERRα-mediated EMT stimulated by TGF-β in endometrial cancer." (PMID 31040369, 2019). "The expression of miR-200a-3p and ZEB1 in the endometrial cancer cell lines was higher than in normal endometrial epithelial cell lines (P < 0.05)." (PMID 38916621, 2024). "In endometrial cancer, ETV5 could promote the invasion potential of tumor cells by up-regulating the expression of the zinc finger E-box binding homeobox 1 (ZEB1) gene and down-regulating the expression of epithelial (E)-cadherin." (PMID 34736492, 2021). "Low dose metformin, at least in endometrial cancer cell lines, appears to reduce the expression of SNAI1, TWIST and ZEB1 and could, therefore, influence the metastatic process, although this has yet to be proven in primary endometrial cancer samples." (PMID 31083574, 2019). "In particular, ZEB1 was not expressed in the normal endometrial epithelium and was aberrantly expressed in tumor epithelial cells of aggressive endometrial cancers." (PMID 25544793, 2014). "Metformin increases epithelial markers such as E-cadherin and pan-keratin in endometrial cancer cells in vitro and decreases mesenchymal markers (e.g., N-cadherin, fibronectin, vimentin) and transcriptional drivers of EMT (e.g., Twist-1, snail-1, zinc finger E-box-binding homeobox-1 [ZEB-1])." (PMID 30211120, 2018).
liver cancer (37 papers, 2013 to 2025). An epithelial or non-epithelial malignant neoplasm that arises from the liver. "Next, to test the hypothesis if the ZEB1 associated metabolic signature in liver cancer cells opens opportunity for therapeutic intervention." (PMID 40830586, 2025). "Our study aims to investigate the apoptotic potential of pharmacological inhibition of mitochondrial metabolism in primary liver cancer and whether this strategy can reduce ZEB1-associated resistance to standard of care chemotherapy Sorafenib." (PMID 40830586, 2025). "We also discuss the emerging therapeutic strategies and future research directions aimed at targeting the ZEB1 molecular network to improve the outcome of liver cancer patients." (PMID 41303618, 2025). "The co-culturing of macrophages treated with exosomes from both groups with liver cancer cells showed that the levels of ZEB-1 and vimentin in liver cancer cells were downregulated, while the level of E-cadherin was upregulated." (PMID 40612677, 2025). "In this review, we aim to give a comprehensive overview of the current knowledge on the biological roles of ZEB1 in the two main subtypes of liver cancer, HCC and CCA." (PMID 41303618, 2025). "We aim to contribute valuable insights into the intricate interplay between ZEB1 and mitochondrial dynamics in primary liver cancer cells, regarding mitochondrial mass and metabolic status." (PMID 40830586, 2025). "Pharmacological inhibition of mitochondrial fission using Mdivi-1 reduced HCC resistance to Sorafenib in ZEB1-driven liver cancer." (PMID 40830586, 2025). "We will first introduce the structural and functional characteristics of ZEB1, followed by a detailed examination of its role in tumor initiation, progression and resistance mechanisms in both types of liver cancer." (PMID 41303618, 2025). "The study showed that Zeb1 was a downstream target of circ_KIAA1429, and circ_KIAA1429 promoted liver cancer progression by targeting Zeb1." (PMID 40723784, 2025). "Nevertheless, in terms of the regulation of ZEB1 expression in liver cancer, most studies are related to ZEB1 degradation by ubiquitination mechanisms." (PMID 41303618, 2025). "CCL5 inhibited the ubiquitination degradation of HIF1α and up-regulated the downstream ZEB1 to promote liver cancer metastasis." (PMID 35589690, 2022). "Some reports have found that miR-141 can inhibit the proliferation of liver cancer cells by targeting sperm-associated antigen 9 (SPAG9), hepatocyte nuclear factor 3β (HNF 3β), zinc finger E-box (ZEB1), and so on." (PMID 34675977, 2021). "Aberrant expression of ZEB1 has been reported to be involved in chemoresistance in several types of cancer, including lung, breast, prostate, and liver cancers." (PMID 34163033, 2021). "For instance, lncRNA ATB promotes the EMT process in liver cancer by regulating the miR-200s/ZEB1/2 pathway." (PMID 30487160, 2018). "Concomitant with the upregulation of SPACA6 levels, elevated expression of the miR-99b∼125a∼let-7e cluster was reported in liver cancer and esophageal squamous cell carcinomas, where it promoted tumor invasion and metastasis through regulation of ZEB1 activity." (PMID 41550951, 2025). "Previous studies have shown that circ-ZEB1 expression is increased in liver cancer." (PMID 39802932, 2025). "Generally, WNT signaling activation disrupts the binding of Glycogen synthase kinase 3 beta (GSK3β) to β-catenin to allow the later to translocate to the nucleus and activate target gene transduction, including ZEB1, but several other molecules can modulate this cascade in liver cancer." (PMID 41303618, 2025). "A previous investigation revealed that circ-ZEB1 is expressed abnormally in liver cancer." (PMID 39802932, 2025).
liver cancer (continued). "In this regard, C-C motif chemokine ligand 5 (CCL5) regulates ZEB1 in liver cancer." (PMID 41303618, 2025). "Thus, understanding ZEB1-related functions in liver cancer may introduce new ways to therapeutically challenge these aggressive malignancies." (PMID 41303618, 2025). "Future research should aim to untangle the complexity of the ZEB1-regulated network to identify potential new therapeutic targets that could be integrated with current therapies to improve the evolving treatment landscape of liver cancer patients." (PMID 41303618, 2025). "Therefore, we believe that ethanol can promote the migration and invasion of HCC cells through the lnc171—mir-873-5p—ZEB1 axis, making HCC malignant, which may be one of the mechanisms by which ethanol causes liver cancer." (PMID 38693503, 2024). "In addition, ZEB1 promotes the epithelialmesenchymal transformation of liver cancer cells." (PMID 23420790, 2013). "For example, ZEB1 activates the expression of the hsa-microRNA-99b/let-7e/microRNA-125a cluster in the HCC cells to promote invasion and advance liver cancer progression." (PMID 41303618, 2025). "ZIP4 regulated the expression of EMT markers (β-catenin, E-cadherin, N-cadherin, Snail, Snail2, ZEB1, and vimentin), indicating that ZIP4 regulation induced EMT in liver cancer." (PMID 39040931, 2024). "Of interest, we found that circ-ZEB1 and circ-AFAP1 are strongly correlated with liver cancer stemness and a poor prognosis, and can regulate the epithelial-mesenchymal transition (EMT) process." (PMID 38053070, 2023). "As a crucial regulator involving in the interaction between CAFs and liver cancer cells, CCL5 promotes HCC metastasis through activation of HIF1α/ZEB1 signaling axis." (PMID 35589690, 2022). "In the cholangiocarcinoma and liver cancer model, SPRR2A is activated by STAT-3, promoting EMT through the interaction with ZEB1." (PMID 34934042, 2021). "In liver cancer, OIP5-AS1 promotes the proliferation, EMT progress and metastasis by downregulating ZEB1 and upregulating miR-186a-5p." (PMID 33092644, 2020). "LncRNA-ATB has been reported to be an endogenous “sponge” that upregulates ZEB1 and ZEB2 by competitively binding to the miR-200 family, thereby inducing EMT and liver cancer invasion." (PMID 33552968, 2020). "Zinc finger E-box binding homeobox 1 (ZEB1) is negative prognostic factor in liver cancer by promoting therapy resistance and tumorigenesis." (PMID 40830586, 2025). "circ-ZEB1 could enhance PIK3CA expression via miR-199a-3p silencing and affecting liver cancer progression." (PMID 39802932, 2025). "ZEB1 is not only a key effector of EMT but is also integrated into complex regulatory networks involving major signaling pathways, which are frequently dysregulated in liver cancers." (PMID 41303618, 2025). "In this study, we found that ZIP4 binds to Ephrin-B1 to inhibit the ubiquitination of Ephrin-B1, regulating the Wnt family member 5A (Wnt5A)/Jun N-terminal kinase (JNK)/ZEB1 signaling pathway and promoting EMT, thereby inducing invasion and metastasis of liver cancer cells." (PMID 39040931, 2024). "MiR-200 could downregulate the expression of ZEB1 and ZEB2 in liver cancer, thereby inhibiting cell invasion and cancer progression." (PMID 36137140, 2022). "Moreover, we selected the regular hepatic cell line (HL-7702) and HCC cell lines (Huh-7, HCC-LM3, MHCC-97H, SMMC-7721) to perform RT-qPCR, revealing the expression of circ-ZEB1 and PIK3CA in liver cancer cell lines." (PMID 35277182, 2022).
liver cancer (continued). "Finally, the expression of ZEB1 and PFKM were examined in human liver cancer specimens and non-tumorous liver tissues using immunohistochemical and Western blot." (PMID 33897890, 2021).